HUWE1 (HECT, UBA and WWE domain containing E3 ubiquitin protein ligase 1)
Diseases named in the same sentence as HUWE1 in open-access papers (continued):
Sharing a sentence is not in itself a finding about the gene and the disease.
hepatocellular carcinoma (2 papers, 2018 to 2025). A malignant tumor that arises from hepatocytes. "During obesity-associated hepatocellular carcinoma (HCC) development, expression of interleukin-6 (IL-6), which results from a chronic low-grade proinflammatory state in white adipose tissue and liver, helps to stabilize Mcl-1 via promotion of GSK3β inactivation and suppression of HUWE1." (PMID 30176860, 2018).
leukaemia (2 papers, 2022 to 2023). "HUWE1 is a ubiquitin E3 ligase, that contributes to the proliferation of leukemia cells, affects the differentiation of human HSCs, and may thus provide a new direction for the targeted treatment of leukemia." (PMID 37038215, 2023).
liver cancer (2 papers, 2022 to 2023). An epithelial or non-epithelial malignant neoplasm that arises from the liver.
lymphoma (2 papers, 2012 to 2020). A malignant (clonal) proliferation of B- lymphocytes or T- lymphocytes which involves the lymph nodes, bone marrow and/or extranodal sites. "High expression of HUWE1 has been demonstrated to specifically correlate with MYC-driven lymphomas, however the role of HUWE1 in regulating MYC in MM is unknown." (PMID 32523091, 2020).
pancreatic cancer (2 papers, 2021). "Furthermore, the analysis showed that certain RNAs such as HUWE1, hsa-miR-6780b-5p, has_circ_0058208 and lnc-G3BP1-3:8 were found to be in central positions of the network, suggesting their importance in promoting pancreatic cancer progression on many levels." (PMID 35528956, 2021).
retinoblastoma (2 papers, 2022 to 2023). A malignant tumor that originates in the nuclear layer of the retina. "Similarly, HUWE1 promotes K63-linked ubiquitinatination of c-Myc, thereby promoting retinoblastoma cell proliferation." (PMID 35874839, 2022).
X-linked mental retardation syndrome (2 papers, 2017 to 2021). "HUWE1 is a large (480 kDa) and highly abundant protein, mutations in which cause X-linked mental retardation syndromes." (PMID 28943312, 2017).
Azoospermia (1 paper, 2025). Absence of any measurable level of sperm,whereby spermatozoa cannot be observed even after centrifugation of the semen pellet. "The HUWE1 gene, in individuals with Sertoli cell-only syndrome (SCOS), is consistently associated with azoospermia, as reported in other studies." (PMID 39932629, 2025).
bone marrow failure (1 paper, 2025). "It is worth noting that potential off-target effects of HUWE1 inhibition warrant caution in clinical trial design—as hematopoietic-specific HUWE1 knockout results in bone marrow failure in murine models." (PMID 40809696, 2025).
cardiac hypertrophy (1 paper, 2021). "Cardiac hypertrophy and left ventricular dysfunction were diminished in conditional cardiac-specific HUWE1 and c-Myc double knockout mice." (PMID 34199773, 2021). "Furthermore, conditional cardiac-specific HUWE1 knockout mice develop spontaneous cardiac hypertrophy, left ventricular dysfunction, and premature death with an increase in c-Myc in the heart." (PMID 34199773, 2021). "Therefore, HUWE1 in the heart could be a potential therapeutic target for cardiac hypertrophy through its interaction with c-Myc." (PMID 34199773, 2021).
Cerebral ischemia (1 paper, 2015). Restriction of arterial blood supply to the brain associated with insufficient oxygenation to support the metabolic requirements of the tissue. "Based on these studies, given that the expression of Gadd45b is affected by UPS, we hypothesize that Huwe1 might play an important role in regulating Gadd45b expression in brain ischemia." (PMID 26698301, 2015).
colorectal tumours (1 paper, 2017). "Thus, we have identified potentially functionally inactivating mutations of HUWE1 in primary colorectal tumours." (PMID 28003334, 2017).
COVID-19 (1 paper, 2024). A disease caused by infection with severe acute respiratory syndrome coronavirus 2. "We found that dysregulation of the Huwe1-Miz1 axis contributed to diminished IFN response in COVID-19." (PMID 39034993, 2024). "Our study highlights the crucial role of the Huwe1-Miz1 axis in regulating the host antiviral response and indicates its dysregulation as a potential contributor to the limited interferon response during COVID-19." (PMID 39034993, 2024). "Targeting the Huwe1-Miz1 axis could provide a promising approach to developing new antiviral therapies against COVID-19." (PMID 39034993, 2024).
developmental and epileptic encephalopathy (1 paper, 2024). An epilepsy associated with developmental impairment that may be due to either the underlying etiology or the superimposed epileptic activity, or both. "Within the cohort of patients experiencing developmental and epileptic encephalopathy (DEE), WES has revealed genetic variants in novel genes (FGF12, GABBR1, GABBR2, ITPA, KAT6A, PTPN23, RHOBTB2, SATB2) and candidate epilepsy-associated genes (CAMTA1, FAT3, GABRA6, HUWE1, PTCHD1)." (PMID 39523358, 2024).
female infertility (1 paper, 2022). Diminished or absent ability of a female to achieve conception.
FG syndrome (1 paper, 2021). "Furthermore, two variants were located on the X-chromosome: one in MED12 underlying FG-syndrome (OMIM #305,450), and a suspected de novo variant in HUWE1 in a female patient (OMIM #309,590)." (PMID 33710394, 2021).
gram-negative bacterial infections (1 paper, 2024). Infections caused by bacteria that show up as pink (negative) when treated by the gram-staining method. "Loss or inhibition of HUWE1 impaired inflammasome activation, and HUWE1-deficient mice showed increased susceptibility to Gram-negative bacterial infections." (PMID 38763335, 2024).
hereditary motor and sensory neuropathy (1 paper, 2018). A group of slowly progressive inherited disorders affecting motor and sensory peripheral nerves. "SLC25A46 and MFN2 are associated with Hereditary Motor and Sensory Neuropathy (HMSN) while HUWE1 is associated with X-linked syndromic mental retardation, Turner type (XMRT)." (PMID 29342083, 2018).
infantile spasms (1 paper, 2019). A rare epilepsy syndrome characterized by onset of epileptic spasms in infants between 2 and 12 months of age, and rarely up to 24 months. "Also, three cases with a hemizygous (two maternally inherited variants and one DNM) CD missense URV in HUWE1 were all with infantile spasm." (PMID 31175295, 2019).
intellectual disability syndromes (1 paper, 2022). "Overall, HUWE1 has been recognized as the most prominent candidate gene linked to multiple intellectual disability syndromes, although defining the functional roles of HUWE1 in the intelligence genotype-phenotype correlation remains challenging." (PMID 35937685, 2022).
intestinal tumours (1 paper, 2017). "We next addressed the consequence of HUWE1 loss of function upon intestinal tumour development." (PMID 28003334, 2017).
ischaemia (1 paper, 2018). "Following the evidence on AMBRA1-mediated mitophagy in relay with HUWE1 and IKKα, we checked the physiopathological relevance of this functional interplay in models of ischaemia." (PMID 30217973, 2018).
metastatic disease (1 paper, 2022). "A recent protein genomics study on PTC reported that the E3 ubiquitin ligase HUWE1 and DUB were upregulated in tumors and metastatic disease." (PMID 35710427, 2022).
Miscarriage (1 paper, 2016). A pregnancy that ends at a stage in which the fetus is incapable of surviving on its own, defined as the spontaneous loss of a fetus before the 22th week of pregnancy. "Our result shows that the expression of HUWE1 is significantly reduced in poor-quality embryos and villi of miscarriage patients, confirming the important role of HUWE1 in embryo maintenance." (PMID 27901130, 2016). "To explore the translational meaning of the mouse embryo study, we collected the discarded embryos in IVF clinic and villi of miscarriage patients and checked whether the expression of HUWE1 is related to human embryo development." (PMID 27901130, 2016). "In conclusion, these results suggest that HUWE1 protein could contribute to preimplantation embryo development and dysregulated expression of HUWE1 could be related to poor embryo development and miscarriage in IVF clinic." (PMID 27901130, 2016). "Furthermore, Western blot result showed that significantly reduced expression of HUWE1 was observed in the villi of miscarriage embryos compared with the normal control, indicating that reduced expression of HUWE1 is related to poor embryo development." (PMID 27901130, 2016). "We then checked the expressionof HUWE1 in villi of miscarriage patients." (PMID 27901130, 2016). "Western blot shows significantly reduced expression of HUWE1 in the villi samples from miscarriage patients, further confirming that HUWE1 may play important roles in embryo development." (PMID 27901130, 2016). "Interestingly, real time PCR shows no significant change of HUWE1 mRNA levels in the miscarriage patients, indicating that the reduced expression of HUWE1 is possibly caused by post-transcriptional modification instead of transcriptional regulation." (PMID 27901130, 2016).
monoclonal gammopathy of undetermined significance (1 paper, 2020). "Compared to pre-malignant PCs from patients with monoclonal gammopathy of undetermined significance (MGUS), HUWE1 mRNA expression levels were significantly increased in bone marrow-derived MM cells, and still higher in leukemic MM cells." (PMID 33116152, 2020).
neuroblastoma (1 paper, 2020). Neuroblastoma (NB) is the most common solid, extracranial childhood tumor. "Affinity purification proteomics with a human neuroblastoma cell line initially identified Huwe1 as an N-Myc binding protein." (PMID 32336296, 2020).
pemphigus (1 paper, 2025). Pemphigus is a group of rare autoimmune diseases that cause blistering of the skin and mucous membranes (mouth, nose, throat, eyes, and genitals).This conditioncan occur at any age, but often strikes people in middle or older age. "Differential expression analysis was conducted to investigate the expression patterns of the five genes (XBP1, FBXO45, SAT2, AIFM1, and ACSL4) and eight other DEGs associated with ferroptosis (G3BP1, WBP11, TET2, IRF8, FASN, GDPD5, H1-4, and HUWE1) in both the pemphigus and control groups." (PMID 40612574, 2025).
pneumococcal infection (1 paper, 2023). Infections with bacteria of the species streptococcus pneumoniae. "Following pneumococcal infection, Huwe1 promotes macrophage apoptosis by ubiquitinating the anti-apoptotic protein Mcl-1 and therefore targeting it for degradation by the proteasome." (PMID 37033482, 2023).
pneumonia (1 paper, 2023). An acute, acute and chronic, or chronic inflammation focally or diffusely affecting the lung parenchyma, caused by an infection in one or both of the lungs (by bacteria, viruses, fungi, or mycoplasma.). "Microarray and qPCR analysis of plaque macrophages identified downregulation of two E3 ubiquitin ligases, Huwe1 and Itch, following pneumonia." (PMID 37033482, 2023).
renal fibrosis (1 paper, 2023). A final common manifestation of a wide variety of chronic kidney diseases characterized by glomerulosclerosis and tubulointerstitial fibrosis. "Meanwhile, although HUWE1 has been reported to mediate EGFR ubiquitination and degradation in renal fibrosis inhibition, their association in cancer remains unclear." (PMID 37813845, 2023).
serous ovarian cancer (1 paper, 2023). "HUWE1 catalytic domain mutations were also seen in a case of PARPi resistant, BRCA1 exon 11 mutant, high grade serous ovarian cancer." (PMID 37491606, 2023). "We confirmed that HUWE1 silencing leads to PARPi resistance using either talazoparib or olaparib in parental SUM149 cells (without sg-GFP) and in another tumour cell line with a pathogenic exon 11 frameshift BRCA1 mutation, UWB1.289 (high grade serous ovarian cancer, referred to as UWB1)." (PMID 37491606, 2023).
Sertoli Cell-Only Syndrome (1 paper, 2025). A type of male infertility in which no germ cells are visible in any of the biopsied SEMINIFEROUS TUBULES (type I) or in which germ cells are present in a minority of tubules (type II). "In the DNA damage and cellular stress response pathway, mutations in HUWE1 were observed in 2 patients from the same family, one of whom exhibited Sertoli cell-only syndrome (SCOS)." (PMID 39932629, 2025).
sickle cell disease (1 paper, 2022). Sickle cell anemias are chronic hemolytic diseases that may induce three types of acute accidents: severe anemia, severe bacterial infections, and ischemic vasoocclusive accidents (VOA) caused by sickle-shaped red blood cells obstructing small blood vessels and capillaries. "In sickle cell disease (SCD), loss of endothelial peroxisome proliferator-activated receptor γ (PPARγ) was found to reduce HUWE1 expression, and HUWE1 was identified to mediate the ubiquitination of p65 for degradation." (PMID 35937685, 2022).
squamous cell lung carcinoma (1 paper, 2015). A carcinoma arising from squamous bronchial epithelial cells. "Indeed, we have shown here that an inverse correlation exists between TIAM1 and HUWE1 (and TIAM1 and c-MET) in squamous cell lung carcinoma." (PMID 25543140, 2015).
tumor (77 papers, 2006 to 2026). "In contrast, our work focuses on a class of compounds marketed as selective inhibitors of the tumor-associated HECT-type E3 HUWE1, which are frequently used as research tools." (PMID 40897715, 2025). "The E3 ligases HUWE1 and tumor necrosis factor receptor-associated factor 6 can ubiquitinate metabolic enzymes including hexokinase 2 and affect tumor growth by regulating glycolysis." (PMID 39823500, 2025). "HUWE1-mediated ubiquitination is a highly coordinated process and deregulation has been linked to tumorigenesis as well as tumor suppression." (PMID 34065298, 2021). "These tumours display increased sensitivity to DNA‐damaging agents and are dependent on high levels of MCL1 for their survival suggesting a potential therapeutic vulnerability of HUWE1‐mutated tumours." (PMID 28003334, 2017). "Consistent with the observed increase in DNA damage, Huwe1‐deficient tumours displayed increased sensitivity to this treatment with significantly higher levels of apoptosis." (PMID 28003334, 2017). "Our finding that, in addition to increased levels of DNA damage, Huwe1‐deficient tumours display additional sensitivity to DNA‐damaging agents is in agreement with previous reports." (PMID 28003334, 2017). "Taken together, these data identify HUWE1 as a bona fide tumour suppressor gene in the intestinal epithelium and suggest a potential vulnerability of HUWE1‐mutated tumours to DNA‐damaging agents and inhibitors of anti‐apoptotic proteins." (PMID 28003334, 2017). "Particularly pertinent to this was our observation of high levels of DNA damage in Huwe1‐deficient tissue and tumours." (PMID 28003334, 2017). "We found that tumours carrying HUWE1 mutations displayed a far higher somatic mutational burden than those with wild‐type HUWE1." (PMID 28003334, 2017). "We observed both increased lysozyme‐positive cell abundance and zone of OLFM4 expression in Huwe1‐deficient tumours." (PMID 28003334, 2017). "Genetic deletion of Huwe1 rapidly accelerated tumourigenic in mice carrying loss of the intestinal tumour suppressor gene Apc, with a dramatic increase in tumour initiation." (PMID 28003334, 2017). "Together, these data demonstrate that loss of Huwe1 leads to accumulation of DNA damage, loss of Apc and subsequent tumour initiation." (PMID 28003334, 2017). "Using intestinal and colonic specific gene deletion, we show that loss of Huwe1 leads to significantly accelerated tumourigenic characterised by a massive increase in tumour incidence." (PMID 28003334, 2017). "Overall, we find that loss of Huwe1 function drives a potent tumour initiation phenotype in the context of Apc heterozygosity." (PMID 28003334, 2017). "Combined, these characteristics could facilitate the selection and expansion of aggressive tumor subclones in HUWE1 deficient conditions, thereby further driving tumor malignancy." (PMID 34065298, 2021). "Given this increased DNA damage even in intestines that were wild‐type for Apc, this could suggest that Huwe1 loss increases tumour initiation by promoting loss of the wild‐type Apc allele." (PMID 28003334, 2017). "We observed increased levels of MCL1 in tumour tissue deficient for Huwe1." (PMID 28003334, 2017). "Interestingly, we observed increased levels of γ‐H2AX in normal intestine and tumour tissue deficient for Huwe1." (PMID 28003334, 2017). "One prediction of increased sensitivity to DNA‐damaging agents upon HUWE1 loss would be that tumours that had low levels of HUWE1 might respond better to therapy." (PMID 28003334, 2017). "Notably, we also observed increased tumour formation initiated directly from LGR5‐positive stem cells in Huwe1‐deficient intestines." (PMID 28003334, 2017). "We next analysed tumour data from TCGA to determine whether HUWE1 loss of function can confer a similar DNA damage phenotype in human disease." (PMID 28003334, 2017).